SEMA3A (semaphorin 3A)
Diseases named in the same sentence as SEMA3A in open-access papers (continued):
Sharing a sentence is not in itself a finding about the gene and the disease.
tumor (continued). "Consistent with the data for lymph node metastasis and tumor stage, patients with HNSCC whose tumors had a low level of SEMA3A staining had a poorer prognosis than those whose tumors had a high level of SEMA3A staining." (PMID 26755661, 2016). "Therefore, SEMA3A may function as a tumor suppressor and is a candidate for HNSCC therapy." (PMID 26755661, 2016). "The abnormal expression levels of semaphorin-3A and MMP-14 appear to promote tumor cell proliferation, which provides direct evidence for its damaging impact on tumor progression and disease prognosis." (PMID 24765144, 2014). "That is, VEGF is the molecule mediating the synergistic effects of semaphorin-3A and MMP-14 on tumor progression and metastasis." (PMID 24765144, 2014). "The action of semaphorin-3A is not limited to the nervous system, as NP1 is expressed on endothelial cells, T cells, keratinocytes and tumor cells." (PMID 24765144, 2014). "The action of Sema3A is not limited to the nervous system as NRP1 is expressed on endothelial cells, keratinocytes, T cells, and tumor cells in breast and prostate cancer." (PMID 23343469, 2013). "Immunohistochemical staining of SEMA3A and NRP1 was performed on 15 normal tongue epithelium specimens and the 43 tumour specimens." (PMID 22926477, 2012). "Contrary to previous reports which observed sema3F and sema3A induced changes in adhesion of tumor cells to fibronectin coated dishes, we could not see any effects of any of the semaphorins we tested on the adhesion to fibronectin of any of the tumor cells used here." (PMID 18818766, 2008). "Among class 3 semaphorins, SEMA3A, SEMA3F, and SEMA3C play distinct roles in tumor biology." (PMID 41009819, 2025). "We observed widespread expression of SEMA3A both within the tumor as well as in adjacent non-neoplastic kidney tissue." (PMID 38609390, 2024). "At endpoint, we observed a significant reduction of intratumoural infiltration by macrophages (F4/80+cells) in tumours from mice treated with αCSF1R regardless of the SEMA3A status." (PMID 38670629, 2024). "The expression of SEMA3A in the tumor cells was negative in 38 cases and positive in 60 cases: 5 cases strongly positive, 17-weakly positive and 36—focal." (PMID 38263416, 2024). "A significant negative correlation was observed between the percentage of progesterone receptor expression and SEMA3A expression in the tumor (p = 0.016, Spearman's R = − 0.25), but not in the vessels (p = 0.82)." (PMID 38263416, 2024). "A significant negative correlation was observed between the percentage of estrogen receptor expression and SEMA3A expression in the tumor (p = 0.04, Spearman's R = − 0.21), but not in the vessels (p = 0.57)." (PMID 38263416, 2024). "While not directly comparable to cells in the lung, flow cytometric analysis of B16.F10 cells grown for 11 days in vivo nonetheless showed expression of SEMA3A within the TME, mainly from tumor cells but also blood endothelial cells (BEC), lymphatic endothelial cells (LEC) and some CD45+ cells." (PMID 38609390, 2024). "The in situ immunophenotypic results were confirmed by FACS analysis of whole-tumour tissues, which further showed no significant SEMA3A-induced changes in other myeloid or T cell (eg, Treg) compartments." (PMID 38670629, 2024). "Tumor cells and stroma, which make up the hypoxic core of the tumor microenvironment, promote the production of VEGF, CCL2, CCL5, CSF-1, EMAP-II, endothelin-2, SEMA3A, oncostatin M, and eotaxin." (PMID 37056346, 2023). "While plexin-A1 clearly conveys sema3A-induced anti-angiogenic signals, the effects of plexin-A1 transduced sema3A signals on tumor cells are not as clear." (PMID 37627074, 2023). "Tumour-cell-derived SEMA3A was identified to inhibit the proliferation of protumoural M2 macrophages and promote the proliferation of antitumoural M1 macrophages, thereby recruiting and activating NK and cytotoxic CD8+ T cells to tumours." (PMID 37685898, 2023).
tumor (continued). "Furthermore, we analyzed the expression of ceRNAs in tumour and control samples using TCGA, GTEx, and CPTAC databases and found that the expressions of LINC00460/EME1/HNRNPAB/PLAUR/SEMA3A were significantly higher in LUAD tissues." (PMID 36091160, 2022). "In vivo, Sema3A overexpression increases CD11b+F4/80+ Mφs accumulation but not CD11b+Ly6C+ monocytic cells, and reduces 4T1-3A+ tumor growth in immune complete BALB/c mice." (PMID 35155237, 2022). "Moreover, SEMA3A, PTPRH and IFIT2 were found to have significant effects on tumour inhibition and functioned as promising therapeutic agents for cancers." (PMID 33145887, 2021). "The RNAseq analysis of four null cell PitNETs and four silent subtype III PitNETs which were more clinically aggressive, demonstrated altered gene expression in tumor microenvironment and immuno-surveillance regulation, e.g., arginase type II (ARG2), semaphorin-3A (SEMA3A), and some HLA genes." (PMID 33808624, 2021). "Correlations between higher levels of SEMA3A, SEMA3C, and SEMA3F and type 1, 2, and 6 infiltrates (C1, C2 and C6), indicated a tumour promoter role of these gene members, as patients belonging to those categories had worse survival characterized with higher proliferation rate and enriched with TGFβ." (PMID 32241267, 2020). "Results obtained from NPC tumor sections and from cell lines transiently expressing LMP1 suggest that LMP1 induces Sema3A expression, which in turn may promote tumor progression in NPC patients." (PMID 32192122, 2020). "Many studies on tumors have shown that Sema3A competes with VEGF for the receptor NRP-1, which inhibits VEGF-mediated angiogenesis, thereby further inhibiting the growth, invasion, and metastasis of tumor." (PMID 31467560, 2019). "The apparent discrepancy between these data on Sema3A activity in GBM may be consistent with its putative ability to engage different receptor complexes and regulate multiple cell types in the tumor microenvironment, also depending on expression levels." (PMID 31052281, 2019). "Immune-related semaphorins such as SEMA3A, SEMA4A and SEMA4D may also affect tumor progression via the influencing the immune system." (PMID 31205625, 2019). "Sema3A, for example, which is generally known as an anti-tumorigenic molecule, seems to have a rather ambivalent role in GBM, and displays a receptor-dependent functional plasticity leading to opposite migratory behavior of tumor cells." (PMID 31052281, 2019). "For example, Sema3A inhibits vascular regeneration in a mouse model of oxygen-induced retinopathy (OIR), and prevents tumor angiogenesis by stimulating endothelial cell apoptosis and normalizing the pericyte coverage of tumor vessels." (PMID 29029510, 2017). "Thus, the prognostic value of Sema3A expression and TAM number was determined for patients with this tumor." (PMID 27351132, 2016). "Therefore, in this study, we detected the expression of SEMA3A in healthy controls and HNSCC patients to investigate its fundamental functions in the tumor progression in HNSCC in vivo and in vitro." (PMID 26755661, 2016). "For example, SEMA3A prevents vascular regeneration in a mouse model of oxygen-induced retinopathy and inhibits tumor angiogenesis by eliciting endothelial cell apoptosis and normalizing the pericyte coverage of tumor vessels." (PMID 24521511, 2014). "Notably, a negative correlation was found between SEMA3A expression and ER and PR levels in tumor cells (p = 0.04, Spearman's R = − 0.21 and p = 0.016, Spearman's R = − 0.25 respectively)." (PMID 38263416, 2024). "We hypothesized that the reason T cell immunity was enhanced by NRP1-deficiency in our tumor models, but not against H7N1 S-flu, was an increased availability of SEMA3A in the former." (PMID 38609390, 2024). "However, they did not study the correlation between the urinary sema3A and tumor grading, as we did." (PMID 39061999, 2024).
tumor (continued). "However, gene-set enrichment analysis showed the overrepresentation of terms related to inflammation and interferon-related pathways in tumours lacking SEMA3A." (PMID 38670629, 2024). "To further establish clinical relevance of the Sema3A/NRP1 axis in GBM, we determined the expression levels of each of the signaling components in GBM specimens by tissue microarray (TMA), in which 68 GBM specimens and 10 non–tumor-bearing brain tissues were included." (PMID 37788099, 2023). "The absence of Sema3A leads to a more M1-like phenotype and a reduced tumor growth." (PMID 36071472, 2022). "Hypoxic tumor cells around dying tumor cells in the TC can also produce various kinds of cytokines regulated by HIF, such as C–C chemokine ligand type 5 (CCL5), CXCL12, vascular endothelial growth factor A (VEGF-A), endothelin (ET)-1, ET-2 and semaphorin-3A (Sema3A)." (PMID 34172088, 2021). "Moreover, the localized delivery of Sema3A effectively tamed tumor angiogenesis, leading to vessel normalization and to a significant inhibition of hypoxia-driven metastatic spreading." (PMID 33537086, 2021). "It is important to note that neither exogenous nor tumour-derived Sema3A had an effect on the viability or growth of primary calvarial osteoblasts and the osteoblast-like cells MC3T3 and Saos-2 after up to 12 (Saos-2), 25 and 28 (MC3T3 and calvarial osteoblasts) days." (PMID 29720701, 2018). "Therefore, we hypothesised that during the development of cancer, especially during the angiogenic process, the elevation of VEGF by tumour cells functions more than SEMA3A and NRP1 plays greater roles with VEGF than with SEMA3A." (PMID 22926477, 2012). "We also determined whether expression of sema3A and sema3F, the best studied np1 and np2 agonists respectively, inhibits tumor development from the non-metastatic, estrogen dependent, np1 expressing MCF-7 cells." (PMID 18818766, 2008). "For example, even though sema3G and sema3A expression did not inhibit at all the development of tumors from MDA-MB-231 and MDA-MB-435 cells respectively, they nevertheless strongly reduced the concentration of tumor associated blood vessels." (PMID 18818766, 2008). "Since sema3A inhibited tumor formation in MDA-MB-231 cell almost completely we could not determine the concentration of blood vessels in this case." (PMID 18818766, 2008). "Expression of sema3A inhibited significantly tumor development while expression of sema3F did not." (PMID 18818766, 2008). "In the case of tumors that develop from np2 expressing MDA-MB-435 cells, we found that the expression of sema3A and sema3D reduced the concentration of blood vessels in resulting tumors by 65% even though tumor development from these cells was not inhibited at all by sema3A." (PMID 18818766, 2008). "Indeed, when we only affect SEMA3A expression in tumor cells (via overexpression or deletion), tumor growth was not affected, consistent with the hypothesis that atttenuation of Treg’s is needed to fully release CD8+ effector T cells." (PMID 38609390, 2024). "Interestingly, although the rest of SEMA3 family members showed significant negative correlation with tumour stem-cell-like features measured by mRNA (RNAss) and DNA methylation (DNAss), expression of SEMA3A, SEMA3C, and SEMA3F were not significantly correlated with RNAss." (PMID 32241267, 2020). "Interestingly, even though Sema3D and sema3E inhibited either proliferation or anchorage free growth of the U87MG cells in-vitro much less effectively than sema3A, they still inhibited subcutaneous tumor development as effectively as sema3A if not more effectively." (PMID 22936999, 2012). "In contrast, expression of sema3A did not inhibit tumor development, while sema3D which binds to both neuropilins, significantly inhibited tumor development from the MDA-MB-435 cells though less potently than sema3G which may be due to the lower expression levels obtained with sema3D in these cells." (PMID 18818766, 2008).
tumor (continued). "A negative relationship between Sema3A and matrix metalloproteinase (MMP) enzymes, which facilitate tumour invasion and metastasis, has been demonstrated in cancer." (PMID 40634736, 2025). "They investigated the expression in the TME of 3 Plexin-A4 ligands, namely Sema3A, Sema6A, and Sema6B, and found that none of them modulated CD8+ T cell infiltration into the tumor bed." (PMID 38329122, 2024). "There were no studies of ANGPTL4, CRABP1, MET, and SEMA3A in Oncomine, but in UALCAN, they were frequently expressed in tumor group than normal tissues." (PMID 35833114, 2022). "In vivo, administration of exogenous Sema3A in mice after paratibial inoculation of KHOS cells increased bone volume in non-inoculated and tumour-bearing legs." (PMID 29720701, 2018). "The experimental results demonstrated that there is a negative correlation between semaphorin-3A and MMP-14 expression in NSCLC, suggesting that these protein levels have negative synergy and promote tumor progression in a collaborative manner." (PMID 24765144, 2014). "The present study demonstrated that low expression of semaphorin-3A and high expression of MMP-14 in NSCLC may promote tumor progression, possibly due to negative synergy, and the combined detection of semaphorin-3A and MMP-14 postoperatively was valuable in the judgment of prognosis." (PMID 24765144, 2014).
cancer (83 papers, 2008 to 2025). A tumor composed of atypical neoplastic, often pleomorphic cells that invade other tissues. "SEMA3A is a suppressor gene, and the loss of its expression is associated with cancer progression and increased drug resistance." (PMID 39940891, 2025). "For example, Sema3A mediates nociception in the context of cancer-associated pain while it has an analgesic effect in the context of neuropathic pain." (PMID 36231105, 2022). "In summary, our two previous studies, along with this study, proved the association between Sema3A and the development and progression of UC, in addition to its valuable use as a noninvasive marker for cancer detection and follow up." (PMID 33546237, 2021). "Beyond the nervous system, Sema3A is also associated with various physiological and pathophysiological processes, such as cell migration, immune responses, angiogenesis, and cancer." (PMID 32102436, 2020). "This study clarified the basic functions of miR-362 and found its target gene, Sema3A; however, the underlying molecular pathway of Sema3A, the higher expression of miR-362 in cancer, and the mechanism of miR-362 upregulation are still unclear." (PMID 30155491, 2018). "Finally, miR-30c was found to target an axonal guidance molecule associated with proliferation in cancer, Semaphorin 3A (sema3A)." (PMID 30524229, 2018). "Additionally, an identified EZH2-H3K27me3-enriched promoter region of SEMA3A (Chr7:83,814,596-83,835,002) covers a microsatellite marker that is significantly associated with acute adverse effects following radiotherapy in cancer patients." (PMID 26043758, 2015). "We found that SEMA3B, SEMA3D, SEMA3E, and SEMA3G were all negatively associated with cancer-stem like features, but SEMA3A, SEMA3C, and SEMA3F were positively correlated with DNAss, which indicates that SEMA3s may associate with cancer cell sensitivity or resistance to chemotherapy treatment." (PMID 32241267, 2020). "We hence turned to a cohort of ccRCC patients that had undergone nephrectomy to explore the role of the SEMA3A/NRP1 pathway in human cancer immunity." (PMID 38609390, 2024). "At day ten, when cancer cells have invaded a massive portion of the injected muscles, five factors resulted enriched, including our positive control, Sema3A." (PMID 38195652, 2024). "Semaphorin-3A (SEMA3A) is a membrane protein with diverse roles in cellular processes, including cancer progression and angiogenesis regulation." (PMID 38263416, 2024). "We find SEMA3A expression in both cancer cells and blood and lymphatic endothelial cells within the TME." (PMID 38609390, 2024). "Sema3A is a pleiotropic factor, with known functions in disparate biological processes besides angiogenesis, such as neurogenesis, osteogenesis, cancer progression and immunology." (PMID 39234267, 2024). "Preclinical studies have shown that therapeutic intervention using SEMA3A/SEMA4D antibodies to decrease TAMs is a potential strategy for cancer treatment." (PMID 37685898, 2023). "These experiments demonstrated that SEMA3A-overexpressing cancer cells demonstrated reduced breast tumour growth due to the higher activity of PTEN and MelCAM and reduced expression of vascular endothelial growth factor (VEGF) and phosphorylated FOXO3A." (PMID 37685898, 2023). "Targeting of Sema3A or NRP1 can be an alternative therapeutic approach to inhibit oncogenic TGF-β signaling in cancer." (PMID 37788099, 2023). "This is not surprising, since divergent semaphorin functions in neurons and in cancer cells are commonly seen (e.g. for Sema3A, Sema3E, Sema4D, etc.), likely reflecting the involvement of different receptor complexes and signaling pathways." (PMID 37002363, 2023). "SEMA3A expression in cancer tissues was shown to be an independent prognostic factor of overall survival for various types of cancer, such as oral cancer, gastric cancer, breast cancer, prostate cancer, glioblastoma and ovarian cancer." (PMID 37835781, 2023).